GAPDH (glyceraldehyde-3-phosphate dehydrogenase)
Diseases named in the same sentence as GAPDH in open-access papers (continued):
Sharing a sentence is not in itself a finding about the gene and the disease.
tumor (continued). "Further exploration of the intricate interplay between GAPDH’s metabolic and non-metabolic functions is helpful for us to better understand how it is involved in tumor initiation and progression." (PMID 38611852, 2024). "Interestingly, TEVs isolated from the serum of 4T1-GFP tumor-bearing mice on reserpine chow carried less FLOT-1, and ALIX and GAPDH with post-translational modifications." (PMID 38405101, 2024). "Together, these results suggested that tumour cells lacking the GAPDH redox switch are less well equipped to counteract oxidative stress and hence have a lower probability of survival in the host environment." (PMID 37024754, 2023). "Other work has analyzed tumor versus non-tumor pairs in 195 cases, identifying substantial overexpression of GAPDH in CRC cases." (PMID 38134011, 2023). "It is noteworthy that the overexpression of GAPDH, but not of the other glycolytic enzymes studied, promoted tumor cell survival and resistance to chemotherapy in caspase-independent cell death by preserving a small number of intact mitochondria." (PMID 36837761, 2023). "FLNA, GAPDH, glutathione S-transferase P1 (GSTP1), and galectin-1 (LGALS1) were related to the I-kappaB kinase/NF-kappaB signaling pathway, which was closely related to the apoptosis process of tumor cells." (PMID 37124724, 2023). "In addition, some SNO proteins can participate in the proliferation, metastasis, and apoptosis of CRC by regulating the tumor endocrine and metabolic pathways, such as PKM, GAPDH, LDHA, GLUD1, and PTGES3." (PMID 37124724, 2023). "GAPDH inhibitor, Dimethyl fumarate (DMF), is reported to facilitate the oxidative pentose phosphate pathway (PPP) while inhibiting glycolysis and OXPHOS in tumor cells." (PMID 36200045, 2022). "Reduction of the cellular material for the PCR validation also may well have reduced the repeatability of the tumor marker PCR assay and prevented validation of our LAMP assay for TERC/GAPDH and MYC GAPDH." (PMID 34790573, 2021). "IHC staining of tumor sections was performed to assess the expression levels of metabolism-related enzymes such as the glucose transporter (GLUT1), glyceraldehyde 3-phosphate dehydrogenase (GAPDH), TCA-cycle enzyme citrate synthase (CS), mitochondrial electron transport complex IVc (Comp." (PMID 34200480, 2021). "For example, in measuring the HER2 protein in samples with low tumor cellularity, we were able to improve the concordance between an immuno-MRM assay and the predicate clinical IHC assay by normalizing the MRM measurements to GAPDH." (PMID 34858420, 2021). "Further studies are needed to investigate the role of the other two enzymes in tumor progression and confirm whether protein modifications of GAPDH and LHDA by Itaconate also play an important anti-tumor role." (PMID 33994862, 2021). "Genipin could induce nuclear GAPDH positivity in PDA cell lines inducing autophagy-related genes, as the formation of autophagic vesicles, while, in vivo, reductions in tumor masses were observed." (PMID 33804240, 2021). "A panel of housekeeping control genes (18S, actin, GAPDH) were directly compared across 3 samples to determine which yields the most consistent results across tumor samples (data not shown)." (PMID 33747961, 2021). "Using GAPDH as a control, KPNA2 in all tumour cell lines was strongly expressed." (PMID 34469024, 2021). "All of the results were normalized to housekeeping gene GAPDH and shown as tumor tissue (TT) relative to non-tumor tissue adjacent to tumor (NAT)." (PMID 32610620, 2020).
tumor (continued). "Immunohistochemical staining of Aldolase A and GAPDH exhibited similar staining profiles with diffusely stained cytoplasm of both neoplastic and non-neoplastic cells of the tumor microenvironment." (PMID 32442224, 2020). "Further analysis showed that the active state of YAP, nonphosphorylated YAP, was higher in the tumor from the obese group than the lean group (14.3 ± 0.3 versus 1.1 ± 0.4% GAPDH, P < 0.001)." (PMID 33381605, 2020). "At this stage, a partial repression of GAPDH is not very successful in immediately producing the desired response of reduced tumor volume." (PMID 31185009, 2019). "Inhibition of two key enzymes in glycolysis: hexokinase (HK) and glyceraldehyde-3-phosphate dehydrogenase (GAPDH) by 2-deoxyglucose (2-DG) and sodium iodoacetate (IA), respectively, reduced MDSCs expansion, leading to a delay in tumor progression via induction of ROS-mediated apoptosis of MDSCs." (PMID 31275326, 2019). "60% of analyzed samples showed PDL1/GAPDH mRNA ratios higher than the average control (0.58 ± 0.2, n=4), the difference between the average PDL1/GAPDH ratios of control and tumor samples was not significant, p=0.2." (PMID 30393513, 2018). "The aim of this study was to prospectively validate a gene expression panel (composed of GAPDH, VIL1, CLU, TIMP1, TLN1, LOXL3 and ZEB2) for detecting circulating tumor cells (CTCs) as prognostic and predictive tool in blood samples from 94 metastatic CRC (mCRC) patients." (PMID 28608814, 2017). "To address the question whether this interaction of GAPDH with PKM2 and GPI occurs in other type of cancer cells, we used an in vivo tumor model system, in which tumor was developed in mice muscle by injecting a carcinogen, 3MC." (PMID 26911935, 2016). "Panel 3 indicates that GAPDH is immunoprecipitated specifically by GAPDH antibody, but not by mouse IgG, suggesting that both PKM2 and GPI are associated with GAPDH in tumor but not in normal tissue." (PMID 26911935, 2016). "In presence of 1 mM MG, association of GAPDH with PKM2 or GPI is not perturbed, but the enzymatic activity of GAPDH is reduced to 26.8 ± 5 % in 3MC induced tumor and 57.8 ± 2.3 % in EAC cells." (PMID 26911935, 2016). "Methylglyoxal has also been found to inactivate glyceraldehyde-3-phosphate dehydrogenase (GA3PD), a key enzyme of the glycolytic pathway, and this inactivation is responsible to a significant extent for the inhibition of glycolysis of tumor cells by methylglyoxal (Halder, Ray & Ray, 1993)." (PMID 27635343, 2016). "The mRNA for interleukin-8, EGFRvIII and for housekeeping genes such as ACTB, GAPDH were detected in the cargo of TMV and tumour-derived exosomes and shown to be transferred to monocytes, brain microvascular endothelial cells and tumour cells, respectively." (PMID 26626416, 2015). "In addition to glycolysis, GAPDH suppression decreases p-AKT and participates in tumor formation and proliferation." (PMID 25859407, 2015). "Similarly, CD49fhiCD24low tumor cells exhibited significantly lower expression of EGR1 (−20-fold, p = 0.02), glucose transporter 3 (SLC2A3; −50-fold, p = 0.03), and GAPDH (−100-fold, p = 0.01) than benign cell counterparts." (PMID 26316122, 2015). "The fold change in RARβ2 mRNA levels normalized to GAPDH was compared between tumor tissues with and without RARβ2 hypermethylation." (PMID 25806093, 2015). "Similarly to that demonstrated in vitro, expression of the glycolytic markers GAPDH and PKM2 was similar in both the epithelium and stroma of tumours from good and poor responders." (PMID 24968221, 2014).
tumor (continued). "We quantified the COX-2 mRNA levels per mg tissue, as well as relative to the levels of two different housekeeping genes GAPDH and B2M, in 60 paired samples of normal colorectal mucosa and corresponding non-necrotic tumor tissue." (PMID 24383454, 2014). "EPOR mRNA was overexpressed in all OSCC tissue samples, indicating a higher level of EPOR in the tumor tissue than in the adjacent non-tumor oral tissue after normalization using GAPDH." (PMID 22639817, 2012). "The expression level of target genes was normalized to internal 18S; the presence of other housekeeping genes ALG9 and GAPDH was examined but was not utilized in calculations because these two genes were not consistently detectable in the tumor samples." (PMID 22720672, 2012). "Further investigations on KA with a focus on selective targeting of tumor-GAPDH and not normal cellular GAPDH would provide an opportunity in understanding and advancing its therapeutic potential." (PMID 22964488, 2012). "GAPDH mRNA levels were positively and significantly correlated to FAZA retention in the murine tumor, whereas no clear association was observed in the xenograft." (PMID 21306648, 2011). "Here, a ∼3-fold down-regulation of miR-101 was confirmed by qRT-PCR analysis using miR-186 and GAPDH as normalization controls, both of which were uniformly expressed in endothelial cells in the presence or absence of tumor cells." (PMID 21297974, 2011). "A recent report in this journal on expression of GAPDH in tumor and non-tumor cell lines clearly demonstrated that GAPDH expression increases under hypoxic conditions in a cell-type specific manner, likely due to HIF-1α induction." (PMID 22023915, 2011). "Regulation of GAPDH mRNA and protein expression as a response to the hypoxic development in the tumor cell environment is not an absolute phenomenon, but occurs as a cell-specific post-transcriptionally regulated event." (PMID 19144146, 2009). "ACTB, GAPDH and GUSB mRNA levels are significantly increased in tumor samples, with changes of about 3.6, 3.5 and 4.7 fold, respectively; while 18S rRNA was revealed to be slightly diminished in tumor samples, in a proportion of approximately 13%." (PMID 19257903, 2009). "Based on these findings and from other studies, our present results suggest that there is also no hypoxia-dependent regulation of GAPDH in the tumor cells from different origin examined in – vitro." (PMID 19144146, 2009). "It should be noted that the median expression ratio between tumor tissue and matched normal mucosa was very low with a maximum over-expression of 1.4-fold for ACT and RPS29 and a maximum expression decrease of 1.7-fold for GAPDH and HPRT." (PMID 19650912, 2009). "As anticipated, hypoxic conditions did not change the level of GAPDH or HPRT-1 in the tumor cells, which served as internal controls (results not shown)." (PMID 19696929, 2009). "Two different endogenous controls (GAPDH and ACTB) were employed to reduce variability that might exist between normal, hyperplastic and tumor-containing mammary tissues." (PMID 17626637, 2007). "Together, these data suggest that the known formation of hypoxic regions within gliobastoma tumor tissue is not accompanied by an upregulation of GAPDH mRNA." (PMID 17597534, 2007). "The survivin/glyceraldehyde-3-phosphate dehydrogenase ratios of tumours were higher than those of non-cancerous tissues (P=0.0003)." (PMID 12373603, 2002). "Tumour-survivin/glyceraldehyde-3-phosphate dehydrogenase ratio did not correlate with histologic type, lymph node metastasis, and stage of tumours." (PMID 12373603, 2002). "The glycolytic genes, HK2, GAPDH and ENO1, were chosen as they mediate early, mid and final stages of glycolysis respectively, and all three ketolytic genes BDH1, OXCT1 and ACAT1 were analysed for MYCN amplification, survivability and tumour stage progression in three NB datasets." (PMID 41420301, 2025).
tumor (continued). "The differential interactome composition indicates a functional shift in EGFR signaling that may drive increased tumor cell adhesion (CD44, ITGB1, FN1), metabolic adaptation (GAPDH, ENO1) and stress response (HSPA4, HSP90AB1), consistent with mechanisms observed in therapy‐resistant CRC phenotypes." (PMID 41319168, 2025). "Furthermore, while glycolytic genes (HK2, GAPDH, ENO1) correlate with poor survival, the analysis cannot establish whether their upregulation drives tumour aggression or is a secondary effect of MYCN‐mediated metabolic reprogramming." (PMID 41420301, 2025). "We have shown previously that the glycolytic function of GAPDH in the malignant T cells is not prominent in the end stage of AITL tumor development since inhibition of GAPDH enzymatic activity with its specific inhibitor, kongenic acid, did not prolong survival of our preclinical AITL mice." (PMID 38897995, 2024). "Notably, the inhibition of GAPDH by compounds such as dimethyl fumarate, which are traditionally used for autoimmune disorders, has demonstrated efficacy in impairing both aerobic glycolysis and OXPHOS within tumor cells." (PMID 39766353, 2024). "Then, further experiments have found that GAPDH depletion may induce and accelerate cellular senescence of tumor through the AMPK network in the absence of DNA damage." (PMID 37352167, 2023). "Interestingly, intracellular Zn2+ overload was found to inhibit glycolysis pathway through blocking the synthesis of NAD + and subsequently inactivating GAPDH, demonstrating the promising potential of ZIF-8 in serving as nanotherapeutic agents for tumor glycolytic regulation." (PMID 36510194, 2022). "HIF-1α, in collaboration with c-Myc, promotes glucose uptake by cells and accelerates tumor cell aerobic glycolysis by increasing the expression of GLUTs (primarily GLUT1 and GLUT3) or additional glycolytic enzymes that rely on HIF-1α (such as LDHA, MCT4, and GAPDH)." (PMID 36276846, 2022). "Importantly, in that study, the detailed tumor histotype was not mentioned and GAPDH was used for normalization." (PMID 36142417, 2022). "While our data does not preclude toxicity arising from DNA damage, given the dynamic roles of GAPDH and GSTP1 in the hypoxic tumour microenvironment, such an effect of N3-AZA on their activities may partially explain the observed hypoxic cytotoxicity of the drug." (PMID 33640700, 2021). "Against this background, the observed three GAPDH phenotypes in Warthin tumor oncocytes (cytoplasmic and nuclear, only nuclear or no GAPDH staining) demonstrated by immunohistochemistry could point to changes in its functional spectrum." (PMID 32365590, 2020). "Since reduced GAPDH protein expression, as seen during immunohistochemistry, does not necessarily correlate with GAPDH mRNA expression levels, quantitative RT-PCR was performed to assess GAPDH transcript levels present in Warthin tumor oncocytes and normal ductal cells." (PMID 32365590, 2020). "Finally, to directly assess the role of the Warburg effect on the proliferative capacity of tumor cells, we analyzed the number of mitosis in hematoxylin-eosin tumor sections and correlated them with the expression levels of PGC-1alpha and GAPDH/MT-CO1 ratio as metabolism biomarkers." (PMID 29192176, 2017). "The three most commonly used endogenous controls in protein expression assays, ACTB, TUBB and GAPDH, all displayed significant elevations in tumor samples, indicating that these proteins may not be as reliable as expected." (PMID 27556505, 2016). "GAPDH accumulation was correlated with non-apoptotic tumor cell death." (PMID 25622250, 2015). "In addition, RARRES3 expression in primary tumors did not lead to differences in the number of circulating tumor cells, as measured by relative levels of human GAPDH to murine B2M." (PMID 24867881, 2014). "Two tumor-bearing mice had human GAPDH mRNA in their saliva, but not their blood." (PMID 25397880, 2014).
tumor (continued). "It will be therefore interesting to investigate how GAPDH could contribute with FDG uptake level and tumor stage in building a composite prognostic marker, possibly also correlating it with the status of known NSCLC oncogenic genes (PI3K, EGFR, KRAS, ALK, etc.)." (PMID 23988223, 2013). "In our hands, GAPDH has consistently been shown to be induced by hypoxia in vitro (unpublished), and Zhong and Simons reached the same conclusion in a study on a diverse selection of tumor and non-transformed cell lines." (PMID 21306648, 2011). "Amplification of EPOR in amplicons <10 Mb was identified in less than 0.7% of tumours (n=8) and was similar to the frequency of amplification of other established non-oncogenic loci such as glyceraldehyde-3-phosphate dehydrogenase (GAPDH), β-actin (ACTB), and β-glucuronidase (GUSB)." (PMID 18349818, 2008). "They showed that GAPDH was not significantly regulated under hypoxic conditions in a panel of human tumor cell lines in vitro, and the expression of the gene examined was not altered after substitution of the GAPDH by the 18S RNA band with subsequent densitometric evaluation." (PMID 17597534, 2007). "Twenty-three genes, which were differentially expressed between adjacent normal and tumor samples, were further selected for Q-RT-PCR analysis and were examined by microarray analysis with several probe level quantile normalization methods using either DDX5 or GAPDH as internal controls." (PMID 17540040, 2007). "Furthermore, it has been observed that GAPDH mRNA expression was not normal in some tumour samples and its distribution exhibited a wide range of values." (PMID 16515701, 2006). "Autoreactivity of the 3′-UTR of GAPDH as well as of the coding and noncoding regions of PKM2, a gene whose product catalyzes the last step of glycolysis and plays an important role in tumor cell proliferation, may indicate that their gene dysfunction promotes carcinogenesis." (PMID 37082114, 2022). "Interestingly, in addition to other genes involved in glycolysis, we also found mRNA of GAPDH, frequently used as a reference gene, to be upregulated in tumor samples compared to normal tissue, indicating that it is not well suited as a reference gene for NSCLC." (PMID 33668151, 2021). "However, the tumor growth is not as affected with complete repression of GAPDH." (PMID 31185009, 2019). "During the later stages of tumor growth even though the perturbations have an immediate effect on the intracellular concentrations of glucose and ATP, their concentrations seem to quickly relax back to the values they would have achieved if GAPDH were not inhibited at all." (PMID 31185009, 2019). "However, in our case, lack of GAPDH in tumor cells may be due to depleted NAD+, probably indicating aberrant anaerobic glycolysis in canine oral tumors." (PMID 30001383, 2018). "Therefore, we can conclude that the regulation of GAPDH mRNA and protein expression as a response to the hypoxic development in the tumor cell enviroment in vitro and in vivo is not an absolute phenomenon, but occurs as a cell-specific post-transcriptionally regulated event." (PMID 17597534, 2007). "While the extracellular tumor-linked roles of PGAM1, LDHA, PKM, TPI1, and PGK1 have not been tested, the anti-tumor actions of ALDOA 13, 18, ENO1 16, 18, and GAPDH 20 were reported." (PMID 37056934, 2023). "In the first, tumor was considered present if any tumor marker (hTERT n=7; TERC/GAPDH>3.12 n=6, MYC/GAPDH>0.155 n=7) was present with or without HPV positivity and tumor absent if all tumor markers were absent regardless of the presence or not of HPV." (PMID 34790573, 2021). "Moreover, the difference in miR210HG expression between tumor tissue and tumor-adjacent normal tissue controls was compared, and the same differences in miR210HG expression were obtained regardless of whether GAPDH or U6, an endogenous reference for lncRNA, was used as the normalizer." (PMID 27673330, 2016).